RNU6-49P (RNA, U6 small nuclear 49, pseudogene)
Synonyms: RNU6-49
Gene: Small nuclear RNA gene on chromosome X (37,870,109 to 37,870,215, forward strand). Ensembl gene ENSG00000206983.
Homologues: Orthologues: chimpanzee U6 (99% identical), chimpanzee U6 (96% identical), rabbit U6 (92% identical), rat U6 (92% identical), dog U6 (90% identical), mouse Gm25652 (88% identical), pig U6 (88% identical), pig U6 (86% identical), guinea pig U6 (82% identical). Paralogues in human: RNU6-12P (96% identical), RNU6-13P (96% identical), RNU6-25P (96% identical), RNU6-32P (96% identical), RNU6-41P (96% identical), RNU6-1 (95% identical), RNU6-17P (95% identical), RNU6-18P (95% identical), RNU6-2 (95% identical), RNU6-3P (95% identical), RNU6-4P (95% identical), RNU6-5P (95% identical), and 1287 more.